MYC (MYC proto-oncogene, bHLH transcription factor)
Diseases named in the same sentence as MYC in open-access papers (continued):
Sharing a sentence is not in itself a finding about the gene and the disease.
osteosarcoma (continued). "MYC overexpression has been associated with poor outcomes in osteosarcoma." (PMID 38562379, 2024). "Furthermore, the signature of the MYC target gene set can properly split osteosarcoma samples into high- and low-risk groups in terms of gender, age, and metastasis, and the survival rate is significantly different." (PMID 37342196, 2023). "By matching clinical information and the MYC target gene expression profile in osteosarcoma patient samples, next, a risk signature incorporating 10 MYC target genes in the TARGET cohort turned out to be an independent prognostic factor in patients suffering from osteosarcoma." (PMID 37342196, 2023). "Thus, we focus on the heterogeneity of osteosarcoma and the association between the MYC target gene set and tumor cells, which were crucial for studying the mechanism of tumor initiation and progression and discovering new approaches to therapy." (PMID 37342196, 2023). "MYC amplification and overexpression have been mechanistically linked in many cancers and have been associated with poor prognosis or increased cell proliferation in osteosarcoma cell lines and human tumors." (PMID 35887382, 2022). "In the training cohort, we could observe that the MYC expression levels were significantly correlated with gender, metastasis, and risk score of osteosarcoma patients." (PMID 36586072, 2022). "Similarly, our results showed that high MYC expression was negatively associated with prognosis and multiple immune infiltrating cells in osteosarcoma patients." (PMID 36059448, 2022). "MYC level, associated with the sensitivity and direction of target gene response, also seems to be associated with different classes of genes as has also been observed in analogous studies in an osteosarcoma cell line." (PMID 34885204, 2021). "Next we studied the potential molecular mechanisms underlying MYC’s function in osteosarcoma." (PMID 29644114, 2018). "In addition, misregulated expressions of MYC are often associated with osteosarcoma oncogenesis and progression." (PMID 30662872, 2018). "In this study, we revealed that MYC expression is significantly elevated in metastatic osteosarcoma samples, and most importantly, high MYC expression is associated with poor patient survival, suggesting that MYC could be an important therapeutic target for osteosarcoma treatment." (PMID 29644114, 2018). "In addition, high MYC expression is associated with poor survival of osteosarcoma patients." (PMID 29644114, 2018). "The oncogene MYC is one of the most commonly activated oncogenic proteins in human tumors, with nearly one-fourth of osteosarcoma showing MYC amplification and exhibiting the worst clinical outcomes." (PMID 39897587, 2025). "The inhibition of MYC-driven super-enhancer signaling can counteract the elimination of the proliferation, migration, and invasion of osteosarcoma cells." (PMID 40646517, 2025). "By regulating the levels of MYC and ICD, the proportion of M1 macrophages and mature dendritic cells were enhanced and thereby strengthening anti-tumor immunity to inhibit MYC-amplified osteosarcoma growth and metastasis." (PMID 39897587, 2025). "In summary, this study presented an effective therapeutic strategy with highly targeted drug delivery efficiency and rational combination treatment for precision therapy of MYC-amplified osteosarcoma." (PMID 39897587, 2025). "MYC-amplified osteosarcoma has been identified as the most malignant subtype, with a 5-year survival rate of less than 40 %." (PMID 39897587, 2025). "Taken together, these findings support a model in which MSMO1 shapes osteosarcoma behavior through coordinated regulation of sterol metabolism, Wnt/β-catenin–c-MYC signaling, and glutamine catabolism." (PMID 41463320, 2025). "In osteosarcoma, MYC overexpression is positively correlated with NF-κB activation, which together promote tumor cell proliferation, invasion, and metastasis." (PMID 40786506, 2025).
osteosarcoma (continued). "•An effective therapeutic strategy was presented for targeted therapy of MYC-amplified osteosarcoma growth and metastasis." (PMID 39897587, 2025). "Previous studies have demonstrated that miR-664b-3p directly targets Rheb, a key regulator of the Rheb/mTOR/c-MYC signalling pathway, which promotes glycolysis and tumour growth in osteosarcoma (OS) cells." (PMID 41004517, 2025). "Our findings further highlight the central role of MYC in orchestrating polyamine-mediated proliferation and survival in osteosarcoma." (PMID 40246846, 2025). "Collectively, these results highlight the pivotal role of the AZIN1-polyamine-MYC axis in governing cell cycle progression in osteosarcoma." (PMID 40246846, 2025). "Overexpression of the proto-oncogene, MYC, is a well-described characteristic of aggressive osteosarcomas." (PMID 38562379, 2024). "Osteosarcoma is characterized by various genetic defects, among which the amplification of the oncogene MYC is considered a significant factor contributing to a poor prognosis." (PMID 38638876, 2024). "Among them, MYC-driven osteosarcoma is characterized by genomic amplification and high expression of the MYC gene." (PMID 38638876, 2024). "The AptaFluorescence protocol was applied to detect c-MYC in doxycycline-inducible c-MYC U2OS human osteosarcoma cells." (PMID 39729513, 2024). "This study delves into the potential of Ro-3306 loaded magnetic-driven hydrogel micro-robots in the treatment of MYC-dependent osteosarcoma." (PMID 38638876, 2024). "Next, we compared PDPK1-regulated genes in CHP-134 cells to those we detected previously in the U2OS osteosarcoma cell line, a cell line that has low levels of c-MYC expression." (PMID 38605297, 2024). "Substantial evidence from prior investigations underscores the crucial role of the MYC-driven SE signaling pathway in osteosarcoma tumorigenesis." (PMID 38481812, 2024). "This study is focused on investigating the therapeutic potential of CDK1 inhibitors for the treatment of MYC-dependent osteosarcoma." (PMID 38638876, 2024). "MYC is one of the most frequently dysregulated oncogenes known so far, highly expressed in various tumors including osteosarcoma." (PMID 38212768, 2024). "MYC-driven osteosarcoma is characterized by genomic amplification and high expression of the MYC gene." (PMID 38638876, 2024). "By integrating the changes in MYC at the gene, transcription, and protein levels, we chose the 143B human osteosarcoma cell line for subsequent MYC-dependent osteosarcoma cell model studies." (PMID 38638876, 2024). "Transcriptomic profiling of osteoblastic osteosarcoma cells demonstrated a higher activation of oxidative phosphorylation, reactive oxygen species, mTORC1, hypoxia signaling pathways, and MYC gene targets in lung metastases than primary and recurrent tissues." (PMID 39359731, 2024). "We have designed and fabricated drug-loaded, magnetic-driven hydrogel micro-robots, and applied them to MYC-dependent osteosarcoma cells, thereby implementing a synthetic lethal strategy that targets CDK1." (PMID 38638876, 2024). "We have confirmed the sensitivity of MYC-dependent osteosarcoma cells to CDK1 inhibition in vitro and have successfully enhanced the chemotherapeutic responsiveness of these cells." (PMID 38638876, 2024). "For instance, MYC inactivation induced proliferative arrest in hematological cancers, whereas MYC inactivation in osteosarcoma resulted in terminal differentiation into bone." (PMID 39766097, 2024). "Another consistent finding in osteosarcoma is the relationship between MYC overexpression and tumor progression leading to poor overall survival." (PMID 38562379, 2024). "In summary, the Ro-3306-loaded magnetic-driven hydrogel micro-robots present a novel strategy for enhancing the chemosensitivity of MYC-dependent osteosarcoma, paving the way for new possibilities in future clinical applications." (PMID 38638876, 2024).
osteosarcoma (continued). "We further demonstrated that MYC is the downstream target of niclosamide in osteosarcoma, most likely via the β-catenin/Myc axis." (PMID 36735625, 2023). "As an example of oncogenes involved in metabolic reprogramming, MYC is well known for its varying amplification in numerous cancers, including osteosarcoma." (PMID 37460542, 2023). "In our prognostic signature, we have identified 10 MYC target genes with prognostic value in osteosarcoma." (PMID 37342196, 2023). "To conclude, the MYC target gene set signature is described as an independent prognostic factor of osteosarcoma that can be most beneficial by merging with more independent datasets and even enhanced by optimizing LASSO outcomes in the future." (PMID 37342196, 2023). "Investigating more fully the role of these MYC target genes in osteosarcoma, we analyzed these genes." (PMID 37342196, 2023). "In osteosarcoma, MYC promotes cell invasion by activating the MEK-ERK pathway and facilitates malignant progression of the tumor." (PMID 37055822, 2023). "Recent studies proved that the aberrant expression of individual MYC target genes is involved with osteosarcoma initiation, progression, and metastasis and thus serves as a predictive and prognostic biomarker for osteosarcoma." (PMID 37342196, 2023). "MYC was overexpressed in osteosarcoma, and higher MYC expression related with metastasis and poor prognosis." (PMID 36807122, 2023). "The SLIT2/ROBO1 axis contributes to the Warburg effect by activating the SRC/ERK/c-MYC/PFKFB2 pathway in osteosarcoma." (PMID 37197432, 2023). "Then, MYC target genes were exploited, which are highly relevant to the survival time of osteosarcoma patients." (PMID 37342196, 2023). "For instance, MYC is amplified in up to 78% of osteosarcomas, 65% of ovarian serous cystadenocarcinomas, 48% of breast cancers, 45% of esophageal cancers and 37% of lung squamous cell carcinomas." (PMID 36959802, 2023). "HMA regulate MYC to inhibit osteosarcoma proliferation and DNA damage repair through PI3K/AKT signaling pathway." (PMID 36717782, 2023). "There are many studies on MYC and osteosarcoma, and MYC has been identified as a prognostic marker of osteosarcoma." (PMID 37342196, 2023). "Subsequently, 87 differentially expressed MYC target genes were identified in osteosarcoma and normal tissues." (PMID 37342196, 2023). "Then, to obtain the predicted consequences of an MYC target gene set signature in osteosarcoma patients." (PMID 37342196, 2023). "The results indicated that osteosarcoma samples showed higher MYC mRNA expression levels than that of corresponding adjacent nontumorous tissues, while MBTPS2 expression levels were relatively low in tumor samples." (PMID 36586072, 2022). "Afterward, we detected the expression levels and effects on osteosarcoma cells metastasis of MYC and MBTPS2, which were involved in the model." (PMID 36586072, 2022). "MYC copy number amplification has also been correlated to the metastatic progression of osteosarcoma (OS), a predominantly pediatric bone cancer that becomes fatal in advanced disease." (PMID 35594991, 2022). "The MYC protein has been reported to play an essential role in regulating rhythmic metabolism in cultured U2OS human osteosarcoma cells." (PMID 36569894, 2022).
osteosarcoma (continued). "Initially, we detected the mRNA expression levels of two autophagy-associated genes, MYC and MBTPS2, in osteosarcoma patients’ tissues through RT-qPCR." (PMID 36586072, 2022). "Results showed that the expression levels of SLC7A7 and ACSS2 were significantly decreased in two osteosarcoma cell groups (U20S and 143B) compared with the osteoblast cell group (hFOB), whereas MYC was up-regulated in osteosarcoma groups." (PMID 36119478, 2022). "Studies have also found that the SLIT2/ROBO1 axis promotes the Warburg effect of osteosarcoma by activating the SRC/ERK/c-MYC/PFKFB2 pathway." (PMID 36387908, 2022). "More important, IHC results showed MYC expression was up-regulated in metastatic osteosarcoma patients." (PMID 36586072, 2022). "To further validate the biological functions of MYC and MBTPS2 in osteosarcoma cells, we depleted MYC expression in 143B and HOS cells with siRNA technology, and elevated the expression levels of MBTPS2 in MG63 and U2OS cells by overexpression plasmid." (PMID 36586072, 2022). "Recently, it has been found that the risk model composed of CD180, MYC, PROSER2, and FATE1 has a great fitting effect on the overall lifetime of osteosarcoma." (PMID 34488541, 2021). "GSVA results indicated an enrichment of gene sets related to the MYC pathway, bile acid metabolism, allograft rejection, NOTCH signaling, and hedgehog signaling in high-risk osteosarcoma patients." (PMID 34095215, 2021). "Previous studies have suggested that transcription factors OCT‐1, AP1, SP1, TNF, SOX2, SOX4, and MYC play an important role in the proliferation of osteosarcoma cells." (PMID 34185412, 2021). "In consistence with the literature, we found EIF4EBP1, MYC, PTGS2 were down-regulated in PAFAH1B3 knockdown osteosarcoma cells, resulting the deficiency in tumor growth and proliferation." (PMID 34136395, 2021). "A total of 46 genes showed an obvious relationship with the OS of osteosarcoma using a p value of less than 0.05 as the selection criteria, of which MYC (HR = 1.5, 95% CI: 1.1−2.2, p = 0.024) and BNIP3 (HR = 1.5, 95% CI: 1.1−2, p = 0.0073) were risk genes." (PMID 34335109, 2021). "Activation of the PI3K/AKT/mTOR axis was to be expected and MYC is a well known driver of osteosarcoma." (PMID 33295144, 2021). "MYC is a potent driver of osteosarcoma tumorigenesis and its transcriptional up-regulation has been associated with resistance to Dox in solid cancers." (PMID 32599901, 2020). "Consistently with these premises, the silencing of GADD45A and MYC chemosensitized Dox-resistant osteosarcoma cells, by disrupting adaptive responses functional to acquire Dox-resistance." (PMID 32599901, 2020). "Consistent with above result, the expression of MYC was higher in metastatic osteosarcoma tissues compared with the primary tissues, and the low expression of MYC predicted a better overall survival in our study." (PMID 32974202, 2020). "Among them, five genes, including CD180, MYC, PROSER2, DNAI1, and FATE1, with significant contribution to the model were selected as the candidate genes in the optimal prognostic risk model of osteosarcoma." (PMID 33082842, 2020). "In human osteosarcoma U2OS MYC-ER cells where BAG1 induction was blocked, activation of MYC resulted in substantial apoptotic cell death." (PMID 30902071, 2019). "Although we and others have demonstrated that BET protein degraders or inhibitors can effectively suppress the expression of SE-driven MYC, BET protein perturbation had negligible effect on MYC protein in osteosarcoma cells." (PMID 30903020, 2019). "CDK9 inhibitors have been shown to synergize with BETi in rhabdoid tumors and osteosarcoma through a c-MYC-dependent and a c-MYC-independent mechanism respectively." (PMID 30841549, 2019).
osteosarcoma (continued). "Analysis of MYC targets in osteosarcoma revealed that most of the osteosarcoma super enhancer genes are bound by MYC." (PMID 29644114, 2018). "In this study, we uncovered that the oncogene MYC is significantly upregulated in metastastic osteosarcoma samples." (PMID 29644114, 2018). "The targeting MYC driven super enhancer signaling using THZ1 represents as a promising therapeutic strategy for the treatment of osteosarcoma." (PMID 29644114, 2018). "We found that MYC preferentially regulates the super-enhancer containing genes and mediates the transcriptional amplification of its target genes in osteosarcoma." (PMID 29644114, 2018). "Our data uncovered novel mechanisms of MYC oncogene in regulation of osteosarcoma and provided important insights for the diagnostics and therapy of osteosarcoma patients." (PMID 29644114, 2018). "We further revealed that THZ1 and JQ1 can efficiently suppress the MYC driven transcriptional amplification and inhibit the osteosarcoma growth, migration, and invasion." (PMID 29644114, 2018). "Overall, our results uncovered the important role of MYC in regulation of osteosarcoma metastasis and patient survival." (PMID 29644114, 2018). "A gain of chromosome 8q bearing the c-MYC locus was detected in three of six H3F3A mutant osteosarcomas." (PMID 28484590, 2017). "Amplification of c-MYC, a member of the MYC transcription factor family tightly involved in the modulation of gene expression and a strong oncogene, has been frequently observed in osteosarcomas." (PMID 28484590, 2017). "H3F3A mutant osteosarcomas frequently showed a gain of chromosome arm 8q involving the c-MYC locus (3/6) and a distinct deletion of 3q13.31 involving LSAMP (2/6)." (PMID 28484590, 2017). "MYC independent mechanisms of tumor cell killing by BET inhibitors have also been reported in other tumors like osteosarcoma cells." (PMID 27259267, 2016). "Some of these genes, or the pathways they regulate, including the PVT1/MYC locus, MET signaling, and IGF1R have been implicated in genetically engineered mouse models of osteosarcoma." (PMID 29056713, 2016). "A human osteosarcoma line U2OS expressing a conditional MYC/ER allele was used for this analysis, as these cells display robust MYC-dependent changes in either cell proliferation or apoptosis, depending on cellular contexts." (PMID 27590350, 2016). "The MYC oncogene is involved in many tumor types, including carcinomas of cervix, lung, breast, colon, and stomach, and also in osteosarcoma." (PMID 25551557, 2014). "MYC amplification in osteosarcoma is common, and MYC expression in this tumor has been correlated with poor prognosis." (PMID 25126591, 2014). "These were, in addition to the known tumor suppressor genes PTEN and DOCK5 and the known oncogene MYC, in total 8 candidate tumor suppressor genes and 4 candidate oncogenes as potential new driver genes in osteosarcoma tumorigenesis." (PMID 25551557, 2014). "Our present results indicate that MYC-dependent osteosarcoma cells are dependent on glucose metabolism through glycolysis for survival compared to osteocytes, their differentiated counterparts." (PMID 24280108, 2013). "MYC suppression in these genetically engineered mouse osteosarcoma cells results in differentiation into osteocytes." (PMID 24280108, 2013). "Previously, an inducible MYC-dependent mouse osteogenic sarcoma cell line was characterized, which upon doxycycline treatment, becomes a differentiated osteocyte." (PMID 24280108, 2013). "We also find that these mouse osteosarcoma cells, upon suppression of their MYC protein levels, display morphological changes and an inhibition of proliferation consistent with a differentiation phenotype." (PMID 24280108, 2013). "Our results indicate the induction of glutaminolysis as the major metabolic difference observed between MYC- dependent osteosarcoma cells and osteocytes." (PMID 24280108, 2013).